TMEM250 (transmembrane protein 250)
Description:
May play a role in cell proliferation by promoting progression into S phase. (Microbial infection) Promotes human herpes simplex virus 1/HHV-1 proliferation.
Synonyms: C9orf69; bA83N9.1
Tractability: Antibody: UniProt predicts a signal peptide or a membrane-spanning region.
Gene: Protein-coding gene on chromosome 9 (136,114,580 to 136,118,946, reverse strand). Ensembl gene ENSG00000238227.
Subcellular location: Membrane; Nucleus; Cytoplasm
Subcellular location (Human Protein Atlas): Nucleoplasm
Gene Ontology:
Molecular function: protein binding
Biological process: positive regulation of cell population proliferation; positive regulation of viral process
Cellular component: cytoplasm; nucleoplasm; nucleus; membrane
Genetic constraint (gnomAD): Loss-of-function variants: 7 observed, 7.24 expected, observed/expected ratio (o/e) 0.97, 90% interval 0.55 to 1.72. That is too few expected variants to judge how well the gene tolerates losing a copy. Missense variants: 196 observed, 208.48 expected, observed/expected ratio (o/e) 0.94, 90% interval 0.84 to 1.06. Synonymous variants: 135 observed, 98.2 expected, observed/expected ratio (o/e) 1.37, 90% interval 1.2 to 1.59.
Homologues: Orthologues: chimpanzee TMEM250 (100% identical), macaque TMEM250 (99% identical), guinea pig TMEM250 (96% identical), mouse Tmem250 (96% identical), rat Tmem250 (96% identical), pig TMEM250 (94% identical), tropical clawed frog tmem250 (83% identical), dog TMEM250 (80% identical), Drosophila melanogaster Septin2 (14% identical), Caenorhabditis elegans unc-61 (14% identical). Paralogues in human: SEPTIN1 (24% identical), SEPTIN5 (23% identical), SEPTIN2 (21% identical), SEPTIN7 (19% identical), SEPTIN3 (19% identical), SEPTIN9 (18% identical), SEPTIN12 (17% identical), SEPTIN8 (17% identical), SEPTIN10 (16% identical), SEPTIN11 (16% identical), SEPTIN14 (16% identical), SEPTIN6 (16% identical).